SIRPA (signal regulatory protein alpha)
Diseases named in the same sentence as SIRPA in open-access papers (continued):
Sharing a sentence is not in itself a finding about the gene and the disease.
tumor (continued). "Thus, the abrogation of the antitumor responses in DT-treated mice indicates that the early activation of SIRPα+CD11+ DCs plays an important role in priming antitumor T cells following CD47KO tumor vaccination." (PMID 31996683, 2020). "For example, genetic engineering has been used tomodify HEK293T cells to generate exosomes that overexpress SIRPα to act as a cancertherapeutic by disrupting CD47-SIRPα interactions between tumor cells and macrophages toattenuate the ability of tumor cells to resist phagocytosis." (PMID 32257533, 2020). "On the other side of the interaction, SIRPα blockade may achieve similar goals via antibody-mediated tumor cell destruction, increased licensing of the cytokine IL-12, and negative regulation of pro-inflammatory pathways." (PMID 35582455, 2020). "Interestingly, treatment with selinexor and ibrutinib favored an anti-tumoral immune response by shifting polarization toward inflammatory M1-like and diminishing PD-1 and SIRPα expression in the remaining tumor-promoting M2-like macrophages." (PMID 32691208, 2020). "We found RQ may decrease the expression levels of CD47 and SIRPα on tumor cells and macrophages, respectively." (PMID 32020472, 2020). "Lamin A/C expression in tumor macrophages may thus reflect levels of SIRPα and might predict the efficiency of immunotherapies targeting the CD47-SIRPα checkpoint in individual patients." (PMID 32854281, 2020). "Exploiting this mechanism, SIRPα competitively inhibits the CD47 protein on tumor cells." (PMID 33126572, 2020). "Additionally, surface expression of SIRPα on splenic and tumor myeloid cells was downregulated in response to AB21 treatment (both alone and in combination with anti-PD-1), but not in the anti-PD1 treatment group." (PMID 33256806, 2020). "Therefore, we investigated the impact of SIRPα antagonism on antitumor immunity in mouse tumor models using hAB21 as a monotherapy or in combination with an antitumor antibody or T cell checkpoint inhibitors." (PMID 33256806, 2020). "CD47 expression on tumor cells can bind to its counter-receptor signal regulatory protein alpha (SIRPα) on macrophages and produces a “don’t eat me” signal, thus serving as an innate immune checkpoint to inhibit phagocytosis of tumor cells and tumor antigen-presenting to T cells." (PMID 32544882, 2020). "Interestingly, the anti-tumor effect of anti-SIRPα mAbs required not only macrophages, but also NK cells and CD8+ T cells." (PMID 32013092, 2020). "SIRPα blockade with hAB21 promoted macrophage-mediated antibody-dependent phagocytosis of tumor cells in vitro and improved responses to rituximab in the Raji human tumor xenograft mouse model." (PMID 33256806, 2020). "Macrophages, an essential component of the tumor ME, express signal regulatory protein α (SIRPα)." (PMID 33178841, 2020). "Blocking SIRPα also polarizes TAMs to an “M1-like” anti-tumor phenotype." (PMID 32456204, 2020). "Therapeutics targeting the CD47/SIRPα axis demonstrated anti-tumor efficacy both in vitro and in vivo in preclinical models and are currently being evaluated in clinical trials for both solid and haematologic malignancies as single agents and as combination therapies with tumor-opsonizing mAbs." (PMID 32456204, 2020). "Competition for FcγR binding between anti-SIRPα antibodies and anti-tumor antibodies may impact macrophage-mediated a ADCP." (PMID 33256806, 2020). "We found that Clo/liposome recovered the tumor burden in mice treated with SIRPα-Fc." (PMID 31829270, 2019). "Next, we tested whether the presence of SIRPα-defined Mo/MΦ subsets in the tumor microenvironment has an impact on patient outcome in FL." (PMID 31611550, 2019). "Additional preclinical studies in syngeneic mouse models demonstrate that anti-SIRPα monotherapy changes the composition of immune cells in the tumor microenvironment with an apparent increase in the number of M1 type macrophages and a concomitant decrease in the M2 type." (PMID 31801627, 2019).
tumor (continued). "Similarly, an antagonistic antibody to the receptor SIRPα enhanced the anti-tumor activity of macrophages and neutrophils against a wide variety of cancer types." (PMID 30621125, 2019). "For instance, immunotherapies combining targeting CD47/signal-regulatory protein alpha (SIRPα), an innate anti-phagocytic axis between tumor cells and macrophages were shown to elicit synergistic anti-cancer activities in both hematologic malignancies and solid tumors." (PMID 31205619, 2019). "CD47, also known as the “don’t eat me” signal, is expressed on normal cells to prevent macrophage engulfment but is often overexpressed on malignant cells to engage its receptor SIRPα found on anti-tumor macrophages and neutrophils in order to prevent phagocytic function." (PMID 30621125, 2019). "Next, we wanted to test whether the subsets of Mo/MΦs were able to phagocytose tumor cells and whether blocking the interaction between SIRPα and CD47 altered the phagocytosis of each subset." (PMID 31611550, 2019). "Interestingly, anti-tumor response was heightened significantly when SIRPα-Fc-CD40L was combined with antibody blockade of CTLA4, PD1, or PDL1." (PMID 30400822, 2018). "Besides, interruption of the ligation of CD47 and SIRPα promotes the tumor cells to be phagocytosed by macrophages in various malignancies." (PMID 30525058, 2018). "We found that soluble mSIRPαext polypeptide, a recombinant extracellular fragment of the mouse SIRPα (mSIRPαext), could promote M1 polarization of macrophages and increase their phagocytic activity to L1210 tumor cells in a CD47-dependent way." (PMID 30105024, 2018). "Interestingly, Notch signal regulated macrophage phagocytosis of tumor cells through SIRPα but in a SHP-1-independent way." (PMID 30105024, 2018). "One mechanism inhibiting the innate response is the presence of the macrophage inhibitory molecule, signal regulatory protein-α (SIRPα), on tumor-associated macrophages (TAMs) and its cognate ligand cluster of differentiation 47 (CD47) on tumor cells in the tumor microenvironment." (PMID 30062558, 2018). "Furthermore, a recent study shows that matrix stiffness increases cell surface expression of SIRPα in macrophages and that marrow-derived macrophages with SIRPα inhibition can effectively clear human tumor xenografts." (PMID 31069313, 2018). "Intensive infiltration of CD8+ T cells indicates that SIRPα-extracellular vesicles could successfully trigger a local immune response at the tumor microenvironment, resulting in tumor regression." (PMID 29850495, 2018). "We then examined whether SIRPα Shp2-iSNAP can also promote the phagocytic power of primary macrophages against tumor cells expressing CD47." (PMID 28883531, 2017). "Since NF-κB is a vital transcription factor in immune response against tumor, this result might uncover that the tumoricidal activity of SIRPα-KD macrophages may be diminished as well." (PMID 27793032, 2016). "At the meantime, our data demonstrated that SIRPα was associated with the phenotype switch of macrophages through NF-κB pathway and played a negative role in tumor migration." (PMID 27793032, 2016). "Knockdown of SIRPα (and therefore mimicking CD47–SIRPα disruption) has also recently been shown to induce migration of macrophages towards tumor cells, strengthen macrophage survival and propagate a proinflammatory cytokine response via NF-κB signaling, which is consistent with an M1-phenotype." (PMID 27092773, 2016). "Furthermore, it has been shown that CD47/SIRPα and SIRPα signaling negatively regulate antibody-dependent elimination of tumor cells, which supports the idea of targeting CD47/SIRPα interaction to enhance the clinical effects of cancer therapeutic antibodies." (PMID 27671753, 2016). "Our data support the usage of PPRHs to diminish CD47/SIRPα interaction by decreasing the expression of both molecules thus resulting in an enhanced killing of tumor cells by macrophages, which might translate into beneficial effects in cancer therapy." (PMID 27671753, 2016).
tumor (continued). "Given that SIRPα can suppress tumor cell survival and more important, SIRPα is induced by ATO treatment in APL cells, the rapid induction of SIRPα in APL cells may serve as a novel prognostic marker for ATO treatment." (PMID 27010069, 2016). "Transwell assay was used to investigate whether SIRPα could regulate macrophages migration and invasion during tumor exposure." (PMID 27793032, 2016). "Apart from TSP-1-related direct modulation of cancer cell behavior through interactions with membrane receptors, the TSP-1/CD47/SIRPα axis is also strongly implicated in controlling tumor immunity, with both positive and negative roles." (PMID 26578962, 2015). "Blockade of CD47/SIRPα axis led to efficient and rapid phagocytosis of multiple tumor cell types." (PMID 26573233, 2015). "While the decrease in tumor growth is mainly attributed to enhanced tumor cell clearance by macrophages under CD47:SIRPα disruption, other studies have noted that alternative mechanisms may explain the antitumor activities of CD47-blocking antibodies." (PMID 26578962, 2015). "Thus, we demonstrated that thymic Sirpα+ cDCs crucially contribute to this novel process of intrathymic tumor immune tolerance." (PMID 22815949, 2012). "Furthermore, CCR2 expression by thymic Sirpα+ cDCs and abundant expression of its ligands, particularly, CCL2 by tumor-bearing mice prompted us to examine the function of thymic Sirpα+ cDCs in tumor-bearing mice." (PMID 22815949, 2012). "Moreover, tumor formation induced the accumulation of Sirpα+ cDCs in IVRs under the control of CCR2-CCL2 axis and enhanced their capacity to take up antigens, resulting in the shift from Treg differentiation to negative selection." (PMID 22815949, 2012). "Thus, tumor development can induce the shift from Treg differentiation to negative selection, together with exaggerated antigen uptake by Sirpα+ cDCs." (PMID 22815949, 2012). "However, SIRPα is not limited to macrophages—it is also expressed on various immune cells including dendritic cells, neutrophils, monocytes, and microglia, where it influences tumor immunity through multiple pathways." (PMID 40926176, 2026). "Intriguingly, tumor-intrinsic SIRPα expression may also regulate T cell function." (PMID 40589735, 2025). "By binding to SIRPα on the surface of myeloid cells, including macrophages, neutrophils, and dendritic cells, it transmits a “don’t eat me” signal, thereby inhibiting the innate immune-mediated phagocytosis of tumor cells and enabling malignant cells to evade immune surveillance." (PMID 41383500, 2025). "Additionally, the CD47/SIRPα axis is being actively explored for its role in various cancers, especially hematological malignancies, to restore macrophage-mediated phagocytosis of tumor cells." (PMID 41233805, 2025). "Furthermore, primary EOC cells derived from ascites and tumor tissue were bound by the SIRPα–αMSLN4D8 LicMAb (MFI ratios 2.1 and 3.3, respectively), αMSLN4D8 mAb (MFI ratios 2.2 and 3.3, respectively), and αCD47 mAb h5F9-G4 (MFI ratios 4.2 and 6.0, respectively)." (PMID 40402266, 2025). "Similarly, an engineered SIRPα-variant-presenting cell membrane-coated magnetic nanoparticle was fabricated to reprogram tumor-associated macrophages (TAMs) and inhibit the CD47-SIRPα pathway, resulting in synergistic activation of the macrophage immune response and controlled tumor progression." (PMID 40114728, 2025). "Therefore, oAd-SA treatment may elicit a stronger tumor-targeting immune response as compared to anti-CD47/SIRPα antibodies alone or control virus." (PMID 40070841, 2025). "In addition, the expression of immunecheckpoint SIRPα was downregulated on macrophages, which isconducive to breaking the immunosuppression of the tumor microenvironment.Meanwhile, mitochondrial targeting of the photosensitizer also enhancedits ability to induce ICD in 4T1 cells." (PMID 40161955, 2025). "However, NDV infection resulted in a significant recruitment of CD45+ SIRPα+ cells to the tumor." (PMID 41322194, 2025).
tumor (continued). "Furthermore, SIRPα may regulate tumor proliferation and survival by either suppressing growth factor signaling or modulating the PI3K/AKT pathway." (PMID 40589735, 2025). "Importantly, consistent with our previous study, we found that anti-SIRPα treatment upregulated PD-L1 expression in TIMs, which suggested that SIRPα blockade therapy may inhibit the immune evasion of the tumor." (PMID 40523887, 2025). "Upon radiotherapy-mediated activation, SIRPα-deficient macrophages in TIME acquire powerful proinflammatory features and conduct antigen presentation that confer a tumoricidal environment highly infiltrated by tumor-specific CTLs, NK cells and inflammatory TANs." (PMID 38167055, 2024). "Studies have shown that targeting CD47 with anti-CD47 or a SIRPα fusion protein containing IgG1 Fc could exert dual effects, disrupting CD47-SIRPα interaction and promoting FcγR-mediated phagocytosis, which results in an enhanced clearance of tumor cells by macrophages and other APCs." (PMID 39335665, 2024). "Thus, in addition to blocking interactions with phagocytes, binding of SIRPα-Fc fusion decoys could potentially alter CD47 signaling in tumor cells." (PMID 38495618, 2024). "Moreover, SIRPα was found to be highly expressed in tumor tissues compared to normal tissues." (PMID 38462636, 2024). "Therefore, this suggests that targeting both sides of the CD47/SIRPα axis could synergistically control tumor growth by enhancing macrophage-mediated antitumor immunity." (PMID 38414061, 2024). "Moreover, the effective dosage of CD47 antagonists may require adjustments in scenarios where tumor cells express both SIRPα and thrombospondin-1 (TSP-1), both of which disrupt the CD47-SIRPα interaction." (PMID 39040441, 2024). "Notably, ACT with A97L–T cells was accompanied by a significantly increased presence of intratumoral F4-80hi macrophages expressing higher levels of SiRPα, which may counter tumor control." (PMID 38828721, 2024). "And abnormalities also involve gene mutations in PTEN, SIRPA, TBK1, the Y chromosome, as well as immune cells and stromal cells such as Treg, MDSCs, TAMs, CAFs, loss of tumor immunogenicity, abnormalities in Indoleamine 2,3-dioxygenase, Ubiquitin-specific protease 12 (USP12), and Hypoxia." (PMID 39567970, 2024). "Furthermore, the concomitant blockade of the CD47/SIRPα axis with tumor-targeting monoclonal antibodies such as trastuzumab may provide a synergistic phagocytic antitumor activity." (PMID 38433837, 2024). "Importantly, SIRPα and Siglec-10 were predominantly concentrated within the non-cancerous cellular cohorts, with a marked expression discernible in clusters of tumor-associated macrophages (TAMs)." (PMID 38971872, 2024). "Therefore, blockade of CD47/SIRPα may not only reprogram macrophages polarization, but also enhance the anti-tumor activity of NK cells." (PMID 36845095, 2023). "Blocking the CD47/SIRPα pathway had promising results in treatment of several solid tumors and hematological cancers such as glioblastoma, lymphoma, and breast cancer and may compel TAMs to phagocytose tumor cells." (PMID 38033495, 2023). "When anti-SIRPα was administered to local HRT, the TME could become a tumoricidal niche that was heavily infiltrated by activated CD8+ T cells, but with limited myeloid-derived suppressor cells and tumor-associated macrophages." (PMID 37291116, 2023). "It has been shown that CD47, which is highly expressed on cancer cells, and regulatory protein α (SIRPα), a macrophage expressing receptor, form checkpoints for innate immunity, inhibiting macrophage-mediated phagocytosis and leading to immune escape of tumor cells." (PMID 37259426, 2023). "Therefore, inhibiting CD47/SIRPα axis has a significant impact on tumor immunotherapy." (PMID 36726125, 2023).
tumor (continued). "As a new immune checkpoint molecule, CD47 on tumor cells is combined with signal-regulatory proteinα(SIRPα)to send “don’t eat me” signal to immune system, playing a key role in tumor cells recognition and immune escape, and gradually becoming an effective target of tumor immunotherapy." (PMID 36211357, 2022). "Moreover, the CD47-expression could competitively bind with SIRPα, prior to tumor cells, leading to enhancing tumor cell phagocytosis by macrophages." (PMID 35292030, 2022). "Moreover, treatment with antibodies to SIRPα or to CD47 promoted antigen cross-priming of CD8+ T cells by cDC2s as well as enhanced the antitumor effect mediated by CTLs in a mouse syngeneic tumor model in vivo." (PMID 35454882, 2022). "Therefore, blocking the interaction between CD47 and SIRPα can enhance tumor therapeutic efficacy." (PMID 36733388, 2022). "Thus, blocking the interaction between CD47 and SIRPα may enhance anti-tumor effects by neutrophils in the presence of tumor-targeting monoclonal antibodies." (PMID 35884427, 2022). "Interestingly, SIRPα and other myeloid regulators are often also expressed on neutrophils, which are the most abundant immune cell in the circulation and are also found in many tumor cell infiltrates." (PMID 35865547, 2022). "Current studies have revealed that monoclonal antibodies targeting CD47 and SIRPα show therapeutic effect in preclinical models of many solid tumors and hematological tumors by promoting macrophage phagocytosis on cancer cells and cancer stem cells, as a new way of tumor immunotherapy." (PMID 35246144, 2022). "Therefore, blocking the CD47/SIRPα cross talk may be a promising approach for cancer immunotherapy either on its own or via integration with other tumor-targeted therapies, as reported in numerous preclinical studies." (PMID 35978372, 2022). "In addition, the existence of SIRPα-Exos also improved the infiltration of CD8+ T cell, suggesting that SIRPα-Exos could efficiently induce tumor phagocytosis and lead to anti-tumor T cell response." (PMID 36733388, 2022). "However, studies have reported that tumor cells can highly express CD47, and abnormal activation of the CD47/SIRPα axis by tumor cells may inhibit the anti-tumor immune response and upregulate the threshold for macrophage phagocytosis." (PMID 36119033, 2022). "SIRPα sends signals that inhibit the prophagocytic, “eat me” signals transmitted by (i) phosphatidylserine, (ii) the engagement of antibody–antigen complexes with the FcR and (iii) the interaction of calreticulin expressed on tumor cells with the LDL receptor-related protein (LRP) receptor." (PMID 36080360, 2022). "Therefore, targeting the CD47/SIRPα axis seems to exhibit very promising efficacy for tumor therapy, which may unlock the therapeutic potential of macrophages." (PMID 35410993, 2022). "We thus tested whether treatment with NI-1701 would enhance ADCP of tumor cells by TAMs/monocytes in vivo but also by tumor-associated DCs, as recent reports highlighted the pivotal role of DCs at triggering antitumor T-cell response following CD47/SIRPα blockade." (PMID 35538512, 2022). "In addition, therapies that block the CD47/SIRPα axis may stimulate phagocytosis of cancer cells in vitro and anti-tumor immune responses in vivo through macrophages and other immune cells." (PMID 35701829, 2022). "Given the predominant role of tumor-specific Tc in RT-induced tumor eradication in Sirpα−/− mice or in WT mice with Sirpα−/− macrophage infusion, we further investigated how RT-activated intratumoral Sirpα−/− macrophages drive the robust expansion of tumor-specific Tc." (PMID 34050181, 2021). "The high expression of immunogenic antigen presentation machinery on intratumoral Sirpα−/− macrophages after IR suggests that, following phagocytosis of tumor cells/debris, Sirpα−/− macrophages may function as antigen-presenting cells to activate tumor-specific Tc." (PMID 34050181, 2021).